HCAR1 (hydroxycarboxylic acid receptor 1)
Diseases named in the same sentence as HCAR1 in open-access papers (continued):
Sharing a sentence is not in itself a finding about the gene and the disease.
cancer (75 papers, 2015 to 2026). A tumor composed of atypical neoplastic, often pleomorphic cells that invade other tissues. "Further studies are warranted to elucidate the underlying role of HCAR1 in lipid metabolism and its wider relevance to cancer treatment." (PMID 41050072, 2025). "Upregulation of the lactate receptor HCAR1 has been associated with cancer progression." (PMID 40333742, 2025). "Similarly, the association of HCAR1 with various cancer types aligns with previous findings." (PMID 37940970, 2023). "Our findings indicate that intracellular lactate uptake is increased in HCAR1 KO cells, which is contrary to reports in cancer biology, where monocarboxylate transporters (MCTs) and lactate uptake is found downregulated in HCAR1 silenced cells." (PMID 40345852, 2025). "Further, a study in cancer cells found that HCAR1 increased glycolysis and reduced oxidative phosphorylation, whereas HCAR1 KO led to lowered glycolysis and higher oxidative phosphorylation." (PMID 40345852, 2025). "Lactate through HCAR1 promotes DNA-damage repair in cancer cells and abolishes IFN-α production in immune cells." (PMID 39904567, 2025). "HCAR1 is highly expressed in numerous types of cancer cells, where it participates in controlling cancer cell metabolism and defense mechanisms, rendering it an appealing target for cancer therapy." (PMID 40233099, 2025). "Nucleus-excluded HCAR1 mutations caused similar effects in U251MG and A549 cancer cells (Source Data 2E)." (PMID 39904567, 2025). "We show HCAR1 has a nuclear localization where it promotes cancer malignancy through chromatin regulation, DNA damage repair, translational regulation, and intranuclear signaling." (PMID 39904567, 2025). "Upon lactate stimulation following HCAR1 knockdown, the pro‐cancer effects were significantly diminished, suggesting a pro‐oncogenic role for lactate‐activated HCAR1 in OS development." (PMID 40956299, 2025). "The lactate-HCAR1-RAS/PI3K signaling cascades identified in this study are the tip of the iceberg of the potential for TME lactate regulation of cancer progression." (PMID 39199589, 2024). "Lactate binds to GRP81 (also known as hydroxycarboxylic acid receptor 1), a member of a subfamily of G protein-coupled receptors, which is upregulated in many cancers." (PMID 37444583, 2023). "Under basal HCAR1 transcriptomic activity (PBS treatment), we observed associations with different cancers, type 2 diabetes, certain immunological disorders and the blood coagulation pathway." (PMID 37940970, 2023). "Processes such as immune regulation, various cancers, and neurodegenerative diseases were significantly enriched for HCAR1 transcriptomic signature." (PMID 37940970, 2023). "Using in silico approaches, we confirmed the published widespread HCAR1 expression throughout an array of cancer types, including OvCa." (PMID 36615018, 2022). "Using data from the public domain, GTEx, widespread expression of HCAR1 is seen in numerous cancers and stages." (PMID 36615018, 2022). "GPR81 (HCAR-1) is a lactate-sensing receptor found on monocytes and other immune cells and also on certain cancer cells." (PMID 31781212, 2019). "Recently, lactate has been reported to regulate gene transcription via the inhibition of histone deacetylases (HDACs) and survival of cancer cells via hydroxycarboxylic acid receptor 1 (HCAR1)." (PMID 26208712, 2015). "Although HCAR1 is mainly expressed in adipocytes and skeletal muscle cells, recent evidence has shown that its expression is abnormally elevated in numerous types of cancer cells, such as pancreatic, bladder, breast, lung, and colorectal." (PMID 40233099, 2025). "Indeed, lactate-mediated HCAR1 activation plays an important role in cancer progression, including angiogenesis, immune evasion, and cell chemoresistance, through both autocrine and paracrine mechanisms." (PMID 40233099, 2025). "Hence, nuclear location-biased signaling of HCAR1 promotes proliferation and survival in cancer cells." (PMID 39904567, 2025).
cancer (continued). "Subsequently, whether Endothall could block the pro‐cancer effects of lactate/HCAR1/ β‐Arrestin2 was further explored." (PMID 40956299, 2025). "Nuclear HCAR1 provides an adaptive fitness for cells to respond to metabolic tweaks through intracellular ligands, as is the case for lactate which augments survival, proliferation and propagation of cancer cells, by acting via N-HCAR1." (PMID 39904567, 2025). "HCAR1 as GPCR for Lactate is highly expressed in many cancers due to the Warburg effect." (PMID 39904567, 2025). "A better understanding of HCAR1 activation and regulation in cancer cells may facilitate the development of novel anticancer therapeutics." (PMID 39199589, 2024). "Targeting the highly active HCAR1 in cancer cells, upstream of the RAS/PI3K signaling, could be an anticancer approach worthy of further evaluation." (PMID 39199589, 2024). "Indeed, HCAR1 is a known modulator of cell metabolism, and its activation leads to a switch towards oxidative phosphorylation in cancer cells, contributing to the induction of a “quiescence” phenotype, together with the effects of its ligand, lactate." (PMID 39766077, 2024). "Apart from MCT1 and 4, GPR81/HCAR1 acts as a receptor for lactate, regulating cancer survival." (PMID 37370686, 2023). "Though HCAR1 could be a good target for cancer therapeutics, the wide expression of HCAR1 in various tissues, such as brain, adipose tissue, retina, and blood vessels and the broad distribution of lactate through circulation, may limit the therapeutic options targeting HCAR1." (PMID 40333742, 2025). "According to recent research, HCAR1 may be involved in cancer metabolism." (PMID 41050072, 2025). "Additionally, HCAR1 seems to modulate the sensitivity of cancer cells to cytotoxic agents." (PMID 33113952, 2020). "However, a couple of studies focusing on the role of HCAR1 in malignancy allude to a lactate–HCAR1 signaling switch, in an autocrine or paracrine way, that could potentiate cancer cell thriving in the TME and facilitate their ability to invade surrounding tissues and spread to distant sites." (PMID 40333742, 2025). "Using PP2A inhibitor Endothall can abolish the dephosphorylation effect of HCAR1 on STAT1/2, inhibit cancer cell proliferation, migration, and cell cycle, and promote apoptosis." (PMID 40956299, 2025). "In recent years, the importance of lactate to the survival and growth of cancer cells has been proven to be achieved in part by its ability to activate the lactate receptor (HCAR1), which is also called GPR81." (PMID 36875841, 2023). "Recent studies have shown that this extracellular lactate participates in promoting cancer cell survival and proliferation by multiple autocrine and paracrine mechanisms via the cell-surface receptor GPR81 (HCAR1 or hydroxycarboxylic acid receptor 1)." (PMID 33806675, 2021). "Therefore, developing a single drug that can simultaneously block HCAR1 and activate HCAR2 would be ideal for cancer therapy." (PMID 40233099, 2025). "Collectively, these findings suggest that HCAR1 is an emerging therapeutic target for a variety of diseases, especially cancers, but there are no HCAR1 agents clinically available to date." (PMID 40233099, 2025). "The signaling cascades for cancer cell biological functions downstream from HCAR1 activation have not been defined." (PMID 39199589, 2024). "Thus, mechanisms to explain such multidimensional involvement of HCAR1 in cancer biology are lacking; in this context, an intracellular mode of action along with possible non-traditional signaling activities of the receptor should be accounted for." (PMID 39904567, 2025). "No drugs targeting HCAR1 have been developed for cancer treatment." (PMID 39199589, 2024). "Moreover, HCAR1 is critical for cancer cell survival only when glucose is absent and in the presence of lactate." (PMID 35574309, 2022).
cancer (continued). "Since we saw ERK1/2 and AKT signaling and these pathways modulate proliferation and survival in cancer cells, we measured homeostatic cell proliferation rate and cell survival upon 5-Fluorouracil (5-FU) challenge in cells containing or not HCAR1 at the nucleus." (PMID 39904567, 2025).
infection (2 papers, 2021 to 2025). The state of being infected such as from the introduction of a foreign agent such as serum, vaccine, antigenic substance or organism. "Subsequently, HCAR1 was stably overexpressed via lentiviral infection in 293T cells." (PMID 40956299, 2025).
HCAR1 also shares sentences with these, for which no sentence is quoted: lung carcinoma (15 papers); Sepsis (9); colorectal cancer (5); brain ischemia (4); Hepatitis (4); pancreatitis (4); atherosclerosis (3); cardiovascular disease (2); Cerebral ischemia (2); colon cancer (2); dyslipidemia (2); inflammatory bowel disease (2); liver fibrosis (2); non-small cell lung carcinoma (2); Acute hepatitis (1); acute kidney injury (1); Arthritis (1); autoimmune hepatitis (1); bladder cancer (1); brain tumors (1); Cachexia (1); cervical squamous cell carcinoma (1); chondrosarcoma (1); Chronic colitis (1); chronic myeloid leukemia (1); cognitive decline (1); Ewing sarcoma (1); fibrosis (1); hepatoblastoma (1); Insulin resistance (1).
A further 20 diseases each share a sentence with HCAR1 in 1 paper.